PDIA3 (protein disulfide isomerase family A member 3)
Diseases named in the same sentence as PDIA3 in open-access papers (continued):
Sharing a sentence is not in itself a finding about the gene and the disease.
gastric cancer (27 papers, 2009 to 2025). A primary or metastatic malignant neoplasm involving the stomach. "Gastric cancer patients having high expression of PDIA3 had a favorable prognosis and this was associated with the involvement of PDIA3 in antigen processing and formation of a complex with MCH class I which induced an immune response." (PMID 32023222, 2020). "It is also remarkable that one of the central nodes of the “Focal Adhesion” network (GO:0005925) is PDIA3, a molecular chaperone reported to influence antigen presentation in gastric cancer, and thus likely to influence the therapeutic response." (PMID 37240307, 2023). "PDIA3 regulates the proliferation, invasion, and migration of many tumors, and PDIA3 knockdown significantly inhibits the proliferation, invasion, and migration ability of multidrug-resistant gastric cancer cells." (PMID 36894874, 2023). "The expression dysregulation of PDIA3 has been assessed in several gastrointestinal cancers, and PDIA3 over-expressions in gastric carcinoma and colon cancer have been proven." (PMID 35860021, 2022). "In cervical cancer or gastric cancer PDIA3 was decreased, whereas in laryngeal cancer or aggressive prostate cancers PDIA3 was up-regulated." (PMID 33095243, 2020). "In ESCC, we found that PDIA3 decreased gradually with the progress of stage and related to favorable prognosis, which was in accord with the findings in gastric cancer, but contrary to those in hepatocellular carcinoma." (PMID 31886273, 2019). "Down-regulation of PDIA3 also correlated with increased tumour invasion and advanced stage of gastric cancer." (PMID 27566066, 2016). "Expression levels of PDIA3 have been found in in vivo and in vitro models of gastric cancer." (PMID 40729375, 2025). "The hub proteins identified, CAT, PLEKHA4, HSP90AB1, TXN, EEF2, H6PD, and PDIA3, may play important roles in the treatment of gastric cancer using nintedanib." (PMID 38406279, 2024). "One of the proteins in the family of disulfide isomerase, termed PDIA3, is considered as a prognostic marker in esophageal cancer and also in other cancers, such as gastric cancer; the survival prospect is favorable when the PDIA3 level was high when compared to when it was low." (PMID 34830970, 2021). "For example, a lack of PDIA3 expression has been correlated with increased tumor invasion and the advanced stage of gastric cancer, and has therefore been proposed as a good prognostic marker." (PMID 23782473, 2013). "A lack of PDIA3 expression also correlates with increased tumor invasion and advanced stage of gastric cancer and has therefore been proposed to be a negative prognostic marker." (PMID 20035634, 2009).
glioma (23 papers, 2014 to 2025). A benign or malignant brain and spinal cord tumor that arises from glial cells (astrocytes, oligodendrocytes, ependymal cells). "PDIA3 shines as an emergent biomarker in endometrial carcinoma and is furthermore cataloged as an immune checkpoint hallmark within gliomas." (PMID 38761176, 2024). "In these studies, PDIA3 resulted as a potential key gene affecting the overall survival time of patients with glioblastoma, and high levels of PDIA3 expression have been linked to poor overall survival in glioma patients." (PMID 37686085, 2023). "PDIA3 was positively associated with high malignancy of gliomas and worse survival of glioma patients." (PMID 32687065, 2020). "Since our analysis demonstrated that PDIA3 was correlated with inflammation in gliomas, we subsequently examined seven genes to identify the association of PDIA3 with these inflammatory activity signatures." (PMID 32687065, 2020). "In order to figure out the association between PDIA3 expression levels and gliomas genomic profiles, CNA and somatic mutation analysis were performed in TCGA dataset." (PMID 32687065, 2020). "In gliomas with high PDIA3 expression, somatic mutations showed the correlation with loss of PTEN and amplification of EGFR; meanwhile, in PDIA3 low gliomas, mutations in isocitrate dehydrogenase (IDH) took 80%." (PMID 32687065, 2020). "Due to the location of PDIA3 gene on 15q15.3, a chromosomal band lost in parts of gliomas, we further explored the association between CN and PDIA3 expression." (PMID 32687065, 2020). "In both pan-gliomas and GBMs, tumors with PDIA3 CN loss expressed significantly lower levels of PDIA3 mRNA." (PMID 32687065, 2020). "Since the status of PDIA3 in glioma samples and the association between PDIA3 and immune responses haven’t been clearly clarified, we investigated the landscape of PDIA3 among gliomas using a large-scale bioinformatic analysis." (PMID 32687065, 2020). "Besides, PDIA3 was highly enriched in CL and ME subtype gliomas and served as a sensitive diagnostic marker." (PMID 32687065, 2020). "However, up-regulation of PDIA3 was associated with poor prognosis in gliomas." (PMID 32023222, 2020). "In this study, we identify protein disulfide isomerase A3 (PDIA3) as a crucial factor mediating the vulnerability of glioma cells to ferroptosis and demonstrate that inhibition or depletion of PDIA3 enhances IKE-induced ferroptosis in GBM cells." (PMID 41391030, 2025). "PDIA3 is overexpressed in most cervical cancers, malignant stages of prostate cancer, uveal melanoma, gliomas, clear cell renal cell carcinoma, and hepatocellular carcinoma (HCC)." (PMID 39408858, 2024). "Zhang and collaborators have demonstrated that PDIA3 is involved in inflammation, interaction with other immune checkpoint inhibitors, and suppression of anti-tumor immunity in the glioma microenvironment." (PMID 39408858, 2024). "In TCGA and Chinese Glioma Genome Atlas datasets, PDIA3 is highly correlated with various tumors, and its overexpression has been associated with a poorer prognosis in cervical cancer." (PMID 36894874, 2023). "Overexpression of PDIA3 in GBM reduces the overall survival of patients with glioma by mediating macrophage/microglia pro-tumor activation." (PMID 35401558, 2022). "The immunoblot was used to quantify the PDIA3 expression levels, and the proliferative and invasive ability of glioma cells was determined by colony formation and transwell assays." (PMID 35401558, 2022). "In the GSE102130 glioma dataset, we analyzed 3,321 cells from 6 glioma patients; PDIA3 is highly expressed in malignant cells and monocytes/macrophages in the glioma microenvironment." (PMID 35401558, 2022). "To reveal the role of PDIA3 in glioma cell proliferation and invasion, we designed the following assays." (PMID 35401558, 2022). "Nevertheless, some genes, such as BAX, IFNGR1, and PDIA3, showed a decrease in their copy number and exhibited elevated expression levels in glioma." (PMID 36428756, 2022).
glioma (continued). "A recent study has demonstrated a positive correlation between PDIA3 and estimated scores, different stromal cell types, and invasive immunity in the cancer microenvironment in human gliomas." (PMID 35401558, 2022). "It is found in the study that PDIA3 was expressed in all types of tumors, with the lowest expression in brain lower grade glioma (LGG) and the highest expression in prostate adenocarcinoma (PRAD) in order of expression level from lowest to highest." (PMID 36046686, 2022). "ScRNA-seq was applied to study promotion of the immunosuppressive microenvironment through changes such as the increased expression of protein disulfide isomerase family A member 3 (PDIA3) associated with PTEN loss and EGFR amplification in gliomas." (PMID 34108022, 2021). "Expression levels of risk factors BRCA1, DNM1L, RCN1, HSPB1, RPN2, LRRK2 and SPP1 in high‐grade gliomas were greater than those in lower‐grade gliomas, while the protein expression levels of protective factor PDIA3 were exactly the opposite." (PMID 33611848, 2021). "Increased PDIA3 expression was more correlated with the CL and ME subtypes than PN and NE subtypes in pan-glioma samples." (PMID 32687065, 2020). "In order to study the effects of PDIA3 on the release of chemokines and cytokines and on the viability of GB cells, the PDIA3 gene was silenced in glioma cells or PDIA3 activity was inhibited by the pharmacological inhibitor PUN." (PMID 33153019, 2020). "Here, we reported an attenuation of glioma-induced M2 phenotype when CHME-5 cells were exposed to CMs from PDIA3-silenced T98G cells." (PMID 33153019, 2020). "Using a microglia–glioma interaction cellular model, we investigated the involvement of PDIA3 in functional experiments mimicking the bidirectional interaction between GB (T98G cells) and microglia (CHME-5 cells)." (PMID 33153019, 2020). "The influence of PDIA3 activity inhibition on glioma cell viability was tested after exposure of T98G cells to PUN by flow cytometry analysis with the annexin V-propidium iodide assay." (PMID 33153019, 2020). "In vitro knockdown of PDIA3, decreased cell proliferation, triggered apoptosis, and lowered invasion of glioma cells." (PMID 32590878, 2020). "In view of the increasing clinical benefits of targeting immune checkpoints as the combination therapy, we enrolled several immune checkpoint molecules into correlation analysis to assess their relationship with PDIA3 in glioma samples." (PMID 32687065, 2020). "Meanwhile, PDIA3 was involved in inflammation, interaction with other immune checkpoint inhibitors, and suppression of anti-tumour immunity in the glioma microenvironment." (PMID 32687065, 2020). "PDIA3 was actively involved in some processes facilitating immunosuppression and poor prognosis of glioma patients, including T cell tolerance induction and regulatory T cell differentiation." (PMID 32687065, 2020). "Next, we utilized Kaplan-Meier analysis to investigate the prognostic value of PDIA3 expression in human gliomas." (PMID 32687065, 2020). "PDIA3-silenced T98G cells showed a downregulation of gene expression of COX2 when treated with activating stimuli, reinforcing the idea of the beneficial role of PDIA3 inhibition in glioma patients." (PMID 33153019, 2020). "Here, we investigated expression of protein disulfide isomerase family A member 3 (PDIA3) in gliomas to evaluate its potential as a promising immune target or biomarker." (PMID 32687065, 2020). "Taken together, we elaborated a potential role of PDIA3 as a molecular target in the anticancer therapies of gliomas based on our bioinformatics analysis." (PMID 32687065, 2020). "Subsequently, we evaluated inter-tumor and intra-tumor heterogeneous characteristics of PDIA3 in gliomas." (PMID 32687065, 2020). "To clarify a potential role of PDIA3 in all gliomas, here, we performed analysis based on publicly available databases." (PMID 32687065, 2020).
glioma (continued). "PDIA3 mRNA expression has been shown to be remarkably higher in both low-grade gliomas (oligodendroglioma and astrocytoma) and glioblastomas compared to nontumor controls, as reported in the analysis of gene expression data of gliomas from the Gene Expression Omnibus (GEO) database." (PMID 37686085, 2023). "Moreover, PDIA3 (protein disulfide isomerase A3) is expressed on both glioma cells and microglia, where the expression level is higher in microglia than in microglia in tumor peripheral tissues." (PMID 37700840, 2023). "PDIA3 and B2M have been identified as critical immune modulators and hazardous markers in gliomas." (PMID 35418980, 2022). "Finally, knockdown of PDIA3 significantly weakened the proliferative and invasive ability of glioma cells." (PMID 35401558, 2022). "Additionally, CYP2E1 regulates the level of ER stress and reactive oxygen species, PDIA3 is closely related to the anti‐tumour immunity of glioma, and DNM1L plays a regulatory role in the immune response of NKT cells to tumours." (PMID 33611848, 2021). "Moreover, by using The Cancer Genome Atlas database, we found that overexpression of PDIA3 correlated with about 55% reduction of overall survival of glioma patients." (PMID 33153019, 2020). "In addition, higher PDIA3 expression was associated with worse progression-free survival (PFS) and disease-specific survival (DSS) among pan-glioma patients, LGG, and GBM patients." (PMID 32687065, 2020). "Taken together, these results suggested that PDIA3 might be the predictor for a more aggressive subtype in gliomas and play an important role in the progression of gliomas." (PMID 32687065, 2020). "PDIA3 was found to be upregulated in gliomas and related to suppressive tumor microenvironment, indicating that PDIA3 might be a potential prognostic biomarker or therapy target in the clinical treatment of gliomas." (PMID 32687065, 2020). "In addition, we studied in vitro microglia–glioma interaction to determine the role of PDIA3 in favoring the cross-talk between GB cells and microglia." (PMID 33153019, 2020). "Besides, in diffuse gliomas, high expression of PDIA3 has an influence on glioma progression and predicts worse survival outcome and therapeutic response of glioma patients." (PMID 32687065, 2020). "Additionally, in the 10-immune cell lineage analysis, high PDIA3 expression gliomas were highly correlated with several stromal cells, including epithelial cells, astrocytes and fibroblasts." (PMID 32687065, 2020). "In our study, PDIA3 expression was observed in IDH wild-type gliomas of different grades." (PMID 32687065, 2020). "Therefore, we studied the role of PDIA3 modulation in microglia–glioma interaction, based on the ability of conditioned media collected from human GB cells to induce the activation of microglial cells." (PMID 33153019, 2020). "Thus, we also confirmed that PDIA3 served as a pivotal molecule in immune and inflammatory progression of gliomas." (PMID 32687065, 2020). "Thus, we believed that PDIA3 is vital for glioma cell proliferation and invasion." (PMID 35401558, 2022). "However, ERp57/PDIA3 activity in gliomas is still poorly characterized and could be related to induction of autophagic cell death and apoptosis." (PMID 35109791, 2022). "Thus, our findings supported that PDIA3 might be involved in the infiltration of immune and stromal cells in gliomas microenvironment." (PMID 32687065, 2020). "In addition, it could be speculated that, when PDIA3 is silenced and glioma cells are exposed to an activating stimulus, glioma cells are no longer able to release high amounts of IL6 and IL8 to induce the M2 phenotype in GAMs." (PMID 33153019, 2020). "In order to elucidate specific cell types that might be affected by PDIA3 in tumor microenvironment, we used cell type enrichment analysis to study the association between PDIA3 and 28 populations of immune cells and stromal cells to further explore the role of elevated PDIA3 in gliomas." (PMID 32687065, 2020).
glioma (continued). "Therefore, it is suggested that the combination of PDIA3 and other immune checkpoint inhibitors might be a potential target for glioma therapy." (PMID 32687065, 2020). "Thus, PDIA3 might serve as a crucial mediator in suppressing T cell related anti-tumor immune response in the glioma microenvironment." (PMID 32687065, 2020). "Further research in vivo and clinical studies are warranted to validate the efficacy and safety of PDIA3 inhibition in combination with TMZ, with the ultimate goal of improving patient outcomes in the WHO grade IV gliomas." (PMID 37686085, 2023). "Based on expression data from TCGA and CGGA datasets, PDIA3 was found to be highly correlated with U87 cell lineage and various tumors, including GBM and low grade glioma (LGG)." (PMID 32687065, 2020). "PDIA3 expression was positively correlated with HCK, LCK, MHC-I, MHC-II, STAT1, and interferon, but negatively related to IgG in pan-glioma and GBM analysis based on both TCGA and CGGA datasets." (PMID 32687065, 2020). "PDIA3 was highly positively correlated with HAVCR2, CD274, PDCD1LG2 and others in pan-gliomas and LGG and GBM samples, and PDIA3 demonstrated a high positive correlation with PDCD1LG2 in GBM." (PMID 32687065, 2020). "In pan-glioma analysis of both TCGA and CGGA datasets, the overall survival (OS) of patients with high PDIA3 expression was significantly lower than that of patients with low PDIA3 expression." (PMID 32687065, 2020). "CALR closely interacted with PDIA3 (also known as ERp57) and prolyl 4-hydroxylase β polypeptide (P4HB, also known as PDIA1), which have been reported as prognostic markers in cervical cancer, hepatocellular carcinoma, glioma, and KIRC." (PMID 36338983, 2022). "Based on previous data showing the toxicity of CMs of glioma cells on microglia, we tested the viability and activation status of microglial CHME-5 cells after exposure to B-CM and PS-CM collected from both control and PDIA3-silenced T98G cells." (PMID 33153019, 2020). "Additionally, ROC curve analysis showed that PDIA3 had 84.0% and 71.5% sensitivity and specificity to predict IDH wild-type state gliomas in TCGA and CGGA, respectively, which indicated worse outcome in the progression of glioma." (PMID 32687065, 2020). "We revealed that PDIA3 was positively related to immune score, stromal score, and ESTIMATE score in pan-gliomas with significant trends and in GBM samples with insignificant trends, which indicated that PDIA3 was involved in immune and stromal cells infiltration." (PMID 32687065, 2020). "Conversely, downregulation of the same pathway on glioma cells does not affect microglial viability (tested using CMs obtained from PDIA3-silenced T98G cells on CHME-5 cells)." (PMID 33153019, 2020).